ERBB2 (erb-b2 receptor tyrosine kinase 2)
Diseases named in the same sentence as ERBB2 in open-access papers (continued):
Sharing a sentence is not in itself a finding about the gene and the disease.
breast cancer (continued). "After prognosis analysis, we found four genes (AKT1, ERBB2, KMT2C, and USP34) associated with survival of breast cancer." (PMID 34408553, 2021). "The aim of our study was to determine the function of endogenous Pparγ1 in the onset and progression of mammary tumors induced by ErbB2 in mice." (PMID 33946495, 2021). "In the clinic, the dual EGFR/ERBB2 inhibitors lapatinib and neratinib are used as therapies for ERBB2/HER2-positive breast cancer." (PMID 34737261, 2021). "Crucially, a previous study also expounds that circ-ERBB2 is abnormally expressed in breast cancer cells." (PMID 34732216, 2021). "Circular RNAs (circRNAs) are pivotal regulators of various human cancers and circ-ERBB2 is abnormally expressed in breast cancer cells." (PMID 34732216, 2021). "The gene set originating from the common regions of gains was seen in the study to include oncogenes like ERBB2 as well as tumor suppressor genes, which are common genes not only in breast cancer but in many different cancer types." (PMID 36700096, 2021). "Previously, we reported that the DNA methylation status of PTPRO is a prognostic factor in ERBB2-positive breast cancer." (PMID 34650968, 2021). "We believe that our cutoff value for the ERBB2 estimated CN determined by NGS can be added to the breast cancer treatment guidelines regarding anti-HER2 therapies." (PMID 33710417, 2021). "The treatment of patients with ERBB2 (HER2)-positive breast cancer with anti-ERBB2 therapy is based on the detection of ERBB2 gene amplification or protein overexpression." (PMID 33597560, 2021). "One protein cluster was enriched with kinase domain-containing proteins, such as Src, ERBB2, and ERBB2IP (ERBIN), reinforcing the idea that p140Cap can associate and regulate kinases implicated in breast cancer transformation and progression." (PMID 34708040, 2021). "Expression of chromosome 11 genes such as ErbB2, Septin9, Col1a1, and Chad are elevated in PyMT tumors, as is the case in human breast cancers." (PMID 33235291, 2021). "To test the effect of the drugs on invasiveness, we used a mammary cancer cell line, MT2, expressing full-length Neu (rodent ErbB2), isolated from a murine mammary tumor lung metastasis." (PMID 33939112, 2021). "We confirmed that Bortezomib, similar to experimental tool agent thapsigargin, induced the ER stress in ErbB2-overexpressing breast cancer cell lines and that CHIP KD cells exhibited higher sensitivity to thapsigargin or Bortezomib." (PMID 34439093, 2021). "We then investigated the chromatin-chromatin interactions of the ERBB2 promoter in HER2-high and HER2-low breast cancer cells." (PMID 34575017, 2021). "ERBB2 is a proto-oncogene that is overexpressed in approximately 25% of breast cancers, but also in gastric and other cancers, leading to malignant transformation of epithelial cells." (PMID 33995103, 2021). "Our results suggest that EMT of HER2-positive breast cancer cells results in abrogation of HER2 expression by chromatin-based epigenetic silencing of the ERBB2 gene that leads to trastuzumab resistance." (PMID 34575017, 2021). "Specifically, in HER2/ErbB2-driven breast cancer, CD73 expression by tumor cells and host cells significantly suppressed immune-mediated responses mediated by the anti-ErbB2 blockage." (PMID 33430239, 2021). "The circ-ERBB2 expressions in the tumor tissues of HER2-positive breast cancer patients were tested using quantitative real-time PCR." (PMID 34732216, 2021). "Amplification/overexpression of human epidermal growth factor HER2/ERBB2 is present in 20% of breast cancer." (PMID 34556812, 2021).
breast cancer (continued). "Meanwhile, in patients with HER2-positive breast cancer, we discovered a positive correlation between circ-ERBB2 and TFAP2C expressions." (PMID 34732216, 2021). "It is significant to highlight another point that emerged in this report: the ERBB2 gene is a therapeutic target in breast cancer for which specific drugs exist." (PMID 34746770, 2021). "The scientists also tested this system in ErbB2 overexpressing SKBR3 breast cancer cells, where magnetic contrast agent and SPIONs, tagged with anti-ErbB2, were released rapidly due to enzymatic biodegradation of the microswimmer." (PMID 33562310, 2021). "This was further confirmed by both COSMIC and CCLE outputs identifying ERBB2 as possessing very high CN duplications among patients with breast cancer." (PMID 34259866, 2021). "Luminal breast cancer is positive for oestrogen and progesterone receptors (ER and PR), and can express ERBB2." (PMID 34573857, 2021). "Increased resistance to 5-FU in monotherapy has been attributed to the overexpression of ErbB2 in human breast cancer cells." (PMID 34715860, 2021). "This suggests that ERBB2 status is reflected in breast cancer tissue architecture, and that the information can be captured by and quantified with machine learning." (PMID 33597560, 2021). "One current therapy for ERBB2-positive breast cancer is to use the anti-ERBB2 monoclonal antibody trastuzumab (Herceptin)." (PMID 33801244, 2021). "Taken together, our results suggest that DEPTOR knockdown suppresses cell proliferation and survival by inactivating the PI3K/AKT/mTOR pathway to induce apoptosis in ErbB2-positive breast cancer cells." (PMID 33995662, 2021). "The effect of lapatinib on the abundance of phosphorylated ZFP36/TTP was also demonstrated with another ERBB2-positive breast cancer cell line, BT-474." (PMID 34535639, 2021). "Anti-ErbB2 molecules (for example trastuzumab) are approved for therapy of ErbB2 overexpressing breast cancer or gastric cancer." (PMID 32591879, 2021). "The combination of trastuzumab and chemotherapy is considered a gold standard for ErbB2+ breast cancer treatment." (PMID 34944558, 2021). "In this study, we demonstrate that autophagy promotion by ERBB2 expression protects breast cancer cells from cell death induced by stresses such as chemotherapy drug treatment." (PMID 33801244, 2021). "An amplification in the gene ERBB2 was shown to occur in breast cancer with a high rate of proliferation." (PMID 34439350, 2021). "Many aggressive tumours need autophagy for important tumour-promoting processes (e.g. autophagy enables ERBB2 (Erb-B2 Receptor Tyrosine Kinase 2) trafficking and supports tumourigenesis in ERBB2-driven breast cancer)." (PMID 34706732, 2021). "Disease prognosis was compared in recurrent and/or metastatic ERBB2-positive breast cancer patients treated with neratinib plus paclitaxel vs. trastuzumab plus paclitaxel as the first line of treatment." (PMID 33670524, 2021). "We have shown that ECD overexpression in breast cancer patients correlates with poor prognosis and shorter survival, especially in the ErbB2+ breast cancer subtype." (PMID 33941617, 2021). "Breast cancer harbouring gene amplification of epidermal growth factor receptor 2 (ERBB2, which encodes HER2) or overexpression of HER2 is categorised as HER2+ breast cancer, which occurs in approximately 15%–20% of all breast cancer cases." (PMID 34842356, 2021). "In mice, the deletion or inhibition of PTP1B attenuates the development of mammary tumors driven by mutant ErbB2 (HER-2) as well as their metastases, indicating that PTP1B plays an oncogenic role in the initiation of tumorigenesis." (PMID 34884538, 2021). "To fill this gap of knowledge, we focused on cell line models of ERBB2+ breast cancer (BCa) and used a multidisciplinary approach, including transmission electron microscopy (TEM), biochemistry, and high-resolution mass spectrometry." (PMID 33809102, 2021).
breast cancer (continued). "After prognosis analysis, we found four genes (AKT1 (AKT serine/threonine kinase 1), ERBB2 (Erb-B2 receptor tyrosine kinase 2), KMT2C (lysine methyltransferase 2C), and USP34 (ubiquitin specific peptidase 34)) associated with survival of breast cancer." (PMID 34408553, 2021). "Our bioinformatic analysis of published datasets shows that ERBB2 expression in human breast cancer tissues leads to upregulation of several essential autophagy genes including ATG12." (PMID 33801244, 2021). "Functionally, the interference with circ-ERBB2 repressed HER2-positive breast cancer cell proliferation, migration, invasion and accelerated cell apoptosis." (PMID 34732216, 2021). "Accordingly, the endoplasmic reticulum stress-inducing anticancer drug Bortezomib combined with ErbB2-targeted humanized antibody Trastuzumab showed synergistic inhibition of ErbB2-overexpressing breast cancer cell proliferation." (PMID 34439093, 2021). "ERBB2/HER2 expression, occurring in 10–34% of breast cancer cases, is an important predictor of patient outcome." (PMID 34283045, 2021). "Here, we assessed the expressions of six circRNAs that have been reported to be abnormally expressed in breast cancer: circ_0108942, circ_0001785, circ-ERBB2, circ-BMPR2, circ-UBE2D2, circ-IRAK3." (PMID 34732216, 2021). "We then investigated which common biological parameters that are relevant to breast cancer progression (e.g., ErbB-2, microenvironmental stress) affect the cytoplasmic levels of Cyr61 in tumor cells." (PMID 33540545, 2021). "Patients with ERBB2-positive breast cancer had unfavorable survival rates in the past, but systemic regimens with ERBB2-targeted agents have substantially improved survival outcomes." (PMID 33597560, 2021). "Taken together these data suggest a relevant role for p140Cap as prognostic marker in ERBB2-amplified breast cancer patients, highlighting its tumor suppressor functions in this breast cancer subtype." (PMID 34708040, 2021). "Luminal A, luminal B, basal, ERBB2, and normal-like are the five molecular subtypes of breast cancer from gene expression profiling." (PMID 34573857, 2021). "The HER2 gene (Her2 or ErbB2) is overexpressed in about 20% ~ 30% of malignant tumors, including breast cancer and gastric cancer." (PMID 34146128, 2021). "The sample from stage IIIB had relatively low accumulation of PolII in TSS at the ERBB2 locus, but the gene expression level was comparable with other breast cancer tissues." (PMID 34730297, 2021). "Circ-ERBB2 accelerated HER2-positive breast cancer progression through the circ-ERBB2/miR-136-5p/TFAP2C axis or the circ-ERBB2/miR-198/TFAP2C axis." (PMID 34732216, 2021). "GSE19536 has the same breast cancer subtypes (e.g., luminal, basal, ERBB2, and normal-like) as GSE1456." (PMID 34573857, 2021). "HR+ and ERBB2+ stage 1 breast cancer have a 99% and 95% 5-year survival, respectively, while stage 1 TNBC has an 85% 5-year survival." (PMID 33670942, 2021). "Then, we further explored the relationship between SCD5 expression and HER2/ERBB2 expression by using Oncomine (Gluck breast cancer) and GEO (GSE20194) datasets." (PMID 33903614, 2021). "ECD protein is overexpressed in a significant subset of breast cancers and is also upregulated in other cancers (38, –, 41), and its overexpression correlates with poor prognosis and short survival in ErbB2-overexpressing breast cancers." (PMID 33941617, 2021). "Trastuzumab (trade name Herceptin) is a humanized monoclonal antibody to the extracellular domain of the HER2/neu (ErbB2), a transmembrane receptor overexpressed on the surface of approximately 15–30% of breast cancer cells." (PMID 33987622, 2021). "In patient tissues, the highest K3 expression levels were observed in triple negative and ERBB2 breast cancer tumors where it correlated with amount of tumor infiltrating leukocytes and poor patient prognosis." (PMID 35936112, 2021).
breast cancer (continued). "In fact, it has been shown that EV carrying ERBB2 binds Tz and inhibits its antiproliferative activity on ERBB2 breast cancer cells, likely by a sequestering mechanism." (PMID 33809102, 2021). "Knocking down MDH1 also inhibits fatty-acid synthesis, reducing the survival rate of BT474 cells, which are Erb-B2 receptor tyrosine kinase 2 (ERBB2)-positive breast cancer cells." (PMID 34829545, 2021). "The abundance of key enzymes required for de novo lipogenesis, including sterol regulatory element-binding protein (SREBP1, SREBP2) and fatty acid synthase (FASN) was reduced in Pparγ1−/− vs. Pparγ1+/+ ErbB2 mammary tumors." (PMID 33946495, 2021). "We then tested the long-term activity of Ganetespib in two different genetic mouse models of HER2-positive breast cancer, ErbB2 and Neu mice." (PMID 33500390, 2021). "Epithelial-like breast cancer cells express higher levels of ERBB2 in comparison with mesenchymal-like breast cancer cells due to accessibility of ERBB2 chromatin in the epithelial-like breast cancers." (PMID 34575017, 2021). "This can be at least the partial mechanism for treatment resistance of ERBB2-positive breast cancer contributing to worse survival rates in ERBB2-positive breast cancer patients." (PMID 33801244, 2021). "Approximately 15%–20% of all breast cancers overexpress ErbB2/HER2 and so are classified as HER2+ subtypes, which are associated with aggressive cancers with poor clinical outcomes." (PMID 34343132, 2021). "For instance, the expression of ERBB2 gene is much higher in ERBB2 (HER2) driven breast cancer cell lines, compared to cell lines from other tissue types." (PMID 33750001, 2021). "In general, the interference with circ-ERBB2 repressed HER2-positive breast cancer cell proliferation, migration, invasion and accelerated cell apoptosis." (PMID 34732216, 2021). "Various genomic alterations and genomic signatures, including ERBB2 amplification, mutations in PIK3CA, AKT1, and ESR1, and tumor mutational burden (TMB), have become important biomarkers for treatment selection in breast cancer (BC)." (PMID 33968723, 2021). "For stage I triple-negative tumors, the 5-year breast cancer-specific survival rate is 85%, while that of ERBB2 and hormone receptor-positive cancer ranges from 94% to 99%." (PMID 34109118, 2021). "Induction of expression of the constitutively active N-terminally truncated 95 kD form of HER2/ErbB2 (p95-ErbB2) renders MCF7 breast cancer cells invasive." (PMID 33939112, 2021). "In our study, we found that ErbB2 inactivation dramatically induced autophagy by inducing DEPTOR in ErbB2-positive breast cancer cells." (PMID 33854045, 2021). "Similar beneficial effects of OSU have been reported with lapatinib, another tyrosine kinase inhibitor (ErbB1/ErbB2 inhibitor), in breast cancer and glioblastoma." (PMID 34356673, 2021). "HER3 drives resistance to targeted therapies in a wide range of solid tumors, including ERBB2-amplified (HER2-positive) breast cancer." (PMID 33420373, 2021). "HER2 (ERBB2) is a validated biomarker in breast cancer and HER2 gene amplification or protein overexpression is found in ~20% of newly diagnosed breast cancer patients." (PMID 34741021, 2021). "ERBB2 amplification in breast cancer constitutes 20−30% of all breast cancer cases and is associated with enhanced tumor aggressiveness and reduced patient survival." (PMID 34535639, 2021). "Lapatinib, a potent TKI commonly used in the treatment of HER2-positive breast cancer is a synthetic drug that targets both EGFR and another member is the EGFR family ErbB2 (HER2)." (PMID 33924844, 2021). "Approximately 75% of patients with breast cancer have tumors that are estrogen receptor alpha positive (ER+) and lack amplification of the ERBB2 gene (HER2−)." (PMID 33602273, 2021). "OXTR-induced mammary tumors showed ERBB2 upregulation and mixed histological subtypes with predomination of papillary and medullary carcinomas." (PMID 34099636, 2021).
breast cancer (continued). "Accumulated p21WAF1/CIP1 regulates the ERBB2-mediated proliferation of breast cancer cells and breast carcinogenesis." (PMID 33920506, 2021). "To further determine the mechanism underlying the regulation of these pathways by ErbB2, we transfected two different ErbB2 siRNA oligos into three well-known ErbB2 positive breast cancer cell lines, BT474, SK-BR3, and AU565." (PMID 33854045, 2021). "Since congenital Rlip knockout has differential effects on PyVT-driven and Erbb2-driven mammary carcinogenesis, we examined the expression of a number of genes related to breast cancer by qRT-PCR in breast tumors obtained from all six genotypes." (PMID 34283045, 2021). "p95-ErbB2 is expressed in approximately 30% of the ErbB2-upregulated breast cancers, and that of ErbB2∆Ex16 is approximately 90%11,23,24." (PMID 33795719, 2021). "Mechanically, circ-ERBB2 positively regulated TFAP2C expression through sponging miR-136-5p or miR-198, thereby regulating HER2-positive breast cancer cell function." (PMID 34732216, 2021). "As shown in this study, CHIP plays an essential role as an enforcer of early post-biosynthetic degradation of ErbB2 in ErbB2-driven breast cancer lines." (PMID 34439093, 2021). "This is due to open/active chromatin at the ERBB2 gene in epithelial-like cells, as well as closed/inactive chromatin at the ERBB2 gene in mesenchymal-like breast cancer cells." (PMID 34575017, 2021). "This was also correlated with lower and higher enrichment levels of EMT regulator transcription factors at the cis-regulatory regions of the ERBB2 gene in epithelial-like and mesenchymal-like breast cancer cell lines respectively." (PMID 34575017, 2021). "The clinical evidence that p140Cap correlates with a favorable outcome in ERBB2 breast cancer patients suggest that p140Cap is able to curb the intrinsic biological aggressiveness of ERBB2 tumor." (PMID 34708040, 2021). "On the other hand, similar to ~30% of breast cancers, advanced PyMT tumors express high levels of ErbB2 Indeed, PyMT tumors respond to the EGFR/ErbB2 tyrosine kinase inhibitor lapatinib." (PMID 33235291, 2021). "RANKL stimulation of HER2-positive breast cancer cells overexpressing RANK decreases HER2 phosphorylation, indicating that RANKL influences ErbB2 signaling." (PMID 33785053, 2021). "The ERBB2 gene is amplified or overexpressed in approximately 30% of human breast cancers and in many other cancer types." (PMID 34283045, 2021). "All patient-specific subnetworks contained relevant drug targets that have been largely studied in breast cancer (e.g., ERBB2, ESR1, EGFR, AKT1)." (PMID 33706810, 2021). "In summary, our study uncovered a crucial interplay between DEPTOR and ErbB2 in the regulation of cell proliferation and survival in ErbB2-positive breast cancer cells." (PMID 33995662, 2021). "Accordingly, the endoplasmic reticulum stress-inducing anticancer drug Bortezomib showed synergistic inhibition of ErbB2-overexpressing breast cancer cell proliferation when combined with ErbB2-targeted humanized antibody Trastuzumab." (PMID 34439093, 2021). "The second study reported high inter-site and intra-site reproducibility of ESR1, PGR, ERBB2, and MKi67 mRNA measurements with the MammaTyper® test and showed a precise and reproducible assessment of the four breast cancer biomarkers." (PMID 34371382, 2021). "Pparγ1+/+ ErbB2 mammary tumors showed increased expression of specific chemokines and cytokines (Cxcl5, Cxcl19, Cxcl13, IL1b and Tnfrsf13c)." (PMID 33946495, 2021). "This study highlights the importance of targeting CD73 to potentiate HER2/ErbB2-targeted therapy in breast cancer." (PMID 33430239, 2021). "YY1 is highly expressed in breast cancer and cooperates with activator protein to stimulate the expression of ERBB2 (Her2/neu), a proto-oncogene overexpressed in approximately 30% of breast cancers." (PMID 34063990, 2021).